EIF5A (eukaryotic translation initiation factor 5A)
Description:
Translation factor that promotes translation elongation and termination, particularly upon ribosome stalling at specific amino acid sequence contexts. Binds between the exit (E) and peptidyl (P) site of the ribosome and promotes rescue of stalled ribosome: specifically required for efficient translation of polyproline-containing peptides as well as other motifs that stall the ribosome (By similarity). Acts as a ribosome quality control (RQC) cofactor by joining the RQC complex to facilitate peptidyl transfer during CAT tailing step (By similarity). Also involved in actin dynamics and cell cycle progression, mRNA decay and probably in a pathway involved in stress response and maintenance of cell wall integrity. Also regulates TNF-mediated apoptosis. Mediates effects of polyamines on neuronal process extension and survival. Is required for autophagy by assisting the ribosome in translating the ATG3 protein at a specific amino acid sequence, the 'ASP-ASP-Gly' motif, leading to the increase of the efficiency of ATG3 translation and facilitation of LC3B lipidation and autophagosome formation. (Microbial infection) Cellular cofactor of human T-cell leukemia virus type I (HTLV-1) Rex protein and of human immunodeficiency virus type 1 (HIV-1) Rev protein, essential for mRNA export of retroviral transcripts.
Synonyms: eIF-5A; EIF5A1; MGC99547; MGC104255; FABAS; eIF-4D; eIF5AI
Tractability: Small molecule: a structure with a bound ligand is known. Antibody: UniProt places it where antibodies can reach, with high confidence. PROTAC: ubiquitination databases record sites on it; its protein half-life has been measured.
Gene: Protein-coding gene on chromosome 17 (7,306,944 to 7,312,466, forward strand). Ensembl gene ENSG00000132507.
Subcellular location: Cytoplasm; Nucleus; Endoplasmic reticulum membrane
Subcellular location (Human Protein Atlas): Cytosol; Nucleoplasm; Plasma membrane
Pathways (Reactome):
Metabolism of proteins: Hypusine synthesis from eIF5A-lysine
Gene Ontology:
Molecular function: protein binding; RNA binding; U6 snRNA binding; translation elongation factor activity; ribosome binding
Biological process: cellular response to virus; positive regulation of transcription by RNA polymerase II; translational elongation; tumor necrosis factor-mediated signaling pathway; positive regulation of translational elongation
Cellular component: annulate lamellae; cytoplasm; cytosol; endoplasmic reticulum membrane; membrane; nuclear pore; nucleoplasm; nucleus
Genetic constraint (gnomAD): Loss-of-function variants: 1 observed, 17.08 expected, observed/expected ratio (o/e) 0.0585, 90% interval 0.02 to 0.28. The upper end of that interval is the gene's LOEUF score, 0.28, which puts it in group 1 of 6, group 1 being the genes least tolerant of losing a copy. Missense variants: 29 observed, 204.8 expected, observed/expected ratio (o/e) 0.14, 90% interval 0.1 to 0.19. Synonymous variants: 80 observed, 75.05 expected, observed/expected ratio (o/e) 1.07, 90% interval 0.89 to 1.28.
Homologues: Orthologues: chimpanzee EIF5A (100% identical), mouse Eif5a (100% identical), macaque EIF5A (89% identical), rat Eif5a (88% identical), Drosophila melanogaster eEF5 (69% identical), Caenorhabditis elegans iff-2 (62% identical), Caenorhabditis elegans iff-1 (58% identical). Paralogues in human: EIF5AL1 (98% identical), EIF5A2 (82% identical).
Diseases named in the same sentence as EIF5A in open-access papers:
EIF5A is named in the same sentence as 110 diseases in open-access papers, as found by Europe PMC text mining. Sharing a sentence is not in itself a finding about the gene and the disease. The quoted sentences say what the papers report.
diabetes (17 papers, 2014 to 2025). "Overcoming this challenge is crucial, as examining the tissue-specific loss of DHPS and eIF5A will be important in distinguishing the effects of eIF5A hypusination in each distinct cell type involved in diabetes pathogenesis." (PMID 35448531, 2022). "The growing interest in eIF5A relates to its association with the pathogenesis of several diseases, including cancer, viral infection, and diabetes." (PMID 35163207, 2022). "Hypusine modification of the eukaryotic initiation factor 5A (eIF5A), a highly specific and conserved protein modification, has been linked to cancer, diabetes and infectious diseases." (PMID 24832488, 2014). "eIF5A is considered as a crucial player in several pathologies ranging from cancer to diabetes making it an important therapeutic target for the development of inhibitors." (PMID 39937781, 2025). "In mouse models of diabetes, hyp-eIF5A in pancreatic islet β-cells is responsible for the translation of cytokine-induced transcripts, as well as for the activation and proliferation of T helper cells." (PMID 35163207, 2022). "One aspect of eIF5A in diabetes that is understudied is that of a potential role for the un-hypusinated (eIF5Alys) isoform of the protein." (PMID 35448531, 2022). "In line with our results, a previous study showed that polyamine depletion delayed diabetes onset in NOD mice via diminishing eIF5a hypusination." (PMID 35296698, 2022). "Several aspects of the immune response in diabetes pathogenesis have been found to depend on the hypusination state of eIF5A, both in β cells and in immune cells." (PMID 35448531, 2022). "Since eIF5A is associated with many diseases, such as diabetes, cancers, malaria, and HIV-1 infections, trials aimed at blocking the hypusine modification of eIF5A have been attempted." (PMID 32752130, 2020). "It is also known that eIF5A induces inflammatory cytokine cascade and the nitric oxide synthase iNOS and inhibition of eIF5A protects mice from developing diabetes." (PMID 31310630, 2019). "In the context of T1D, eIF5A participates in the inflammatory cascade leading to β cell dysfunction during the development of diabetes in NOD mice." (PMID 30733517, 2019). "eIF5A is a translation factor dysregulated in several pathologies such as cancer and diabetes." (PMID 39937781, 2025). "The importance of hypusine and eIF5A in the development of diabetes is a burgeoning field of study." (PMID 35448531, 2022). "A second human pathogenesis with a well-defined link to eIF5A is diabetes." (PMID 35163207, 2022). "Similarly, inhibition of eIF5a delayed diabetes and led to an increased number of Tregs in pancreas, pLN, and spleen in a humanized type 1 diabetes mouse model." (PMID 35296698, 2022). "In addition to the role of eIF5A in the diabetes-induced inflammatory response, it has been shown to play a critical role in the development of the pancreas." (PMID 34952646, 2021). "Due to its protective role in inflammation and in macrophage polarization in obesity-induced diabetes eIF5A could be also considered as a potential factor in the improvement of glucose tolerance." (PMID 34952646, 2021). "When small interfering RNA (siRNA) against EIF5A or mice with specific deletion of Dhps in pancreatic islet β cells were used, it was shown that hypusinated EIF5A leads to the development of glucose intolerance in inflammatory mouse models of diabetes, notably by supporting NOS2 translation." (PMID 33326776, 2020). "Thus, it will be very interesting to further analysed GC7 effect on glucose reabsorption functions in mouse models of diabetes in order to determine if eIF5A hypusination inhibition in this context could participate to glucose tolerance improvement." (PMID 33731685, 2021).
diabetes (continued). "Indeed, suppression of eIF5A expression or inhibition of its hypusination induces apoptosis in various mammalian cells, whereas in a mouse diabetes model, reduction of eIF5A expression or inhibition of hypusine modification may cause suppression of apoptosis." (PMID 32605139, 2020). "Previous data from mouse models identified that pharmacological modulation of the hypusination of eIF5A enhanced beta cell mass and improved glucose tolerance in mouse models of both T1D and T2D, thereby suggesting an important role for eIF5AHyp in the setting of diabetes." (PMID 32208453, 2020). "Interestingly, the gene encoding eIF5A is found in the Idd4 diabetes-susceptibility locus in non-obese diabetes (NOD) mice." (PMID 32208453, 2020). "In particular, both isoforms of eIF5A are overexpressed in many types of cancer [for review, see Mathews and Hershey (2015)] and in various others diseases such as HIV-1 infection, malaria, and diabetes." (PMID 33392152, 2020).
breast carcinoma (14 papers, 2016 to 2025). "The MR analysis showed evidence that genetically‐predicted lower expression of EIF5A expression in various CD4+ T cell subtypes was associated with increased risk of breast cancer (OR = 0.96, p = 1.7 × 10−3)." (PMID 41216857, 2025). "In population-based studies, TPMT, TOR2A, KIF11, and EIF5A were reported to be associated with prognosis in other tumours, such as childhood acute lymphoblastic leukaemia, ovarian cancer, breast cancer, and colorectal cancer." (PMID 35421138, 2022). "Importantly, both Snail Family Transcriptional Repressor 1 (SNAI1) and Eukaryotic Translation Initiation Factor 5A (EIF5A) have been associated with the induction of the epithelial-to-mesenchymal transition (EMT) in breast cancer, promotion of breast cancer metastasis, and chemoresistance." (PMID 32873298, 2020). "Recent studies have shown that eIF5A expression is upregulated in multiple cancers, including breast cancer." (PMID 38654332, 2024). "AMD1 activates TCF4 translation by enhancing spermidine production and eIF5A hypusination of breast cancer cells, promoting breast cancer aggressiveness." (PMID 38654332, 2024). "XPO4 has been identified as a tumor suppressor in liver cancer and breast cancer, and its role in the export of eIF5A is known to be critical to the tumor-suppressing effects." (PMID 36182935, 2022). "We have determined that besides its well-defined function in the p38-inflammatory pathway, MKK3 can induce MYC-dependent epithelial-to-mesenchymal transition in breast cancer patients in part through upregulation of EIF5A, EIF5AL1, and SNAI1 genes." (PMID 32873298, 2020). "EIF5A was found to be abnormally expressed in thyroid carcinoma and breast cancer." (PMID 35836612, 2022). "Thus, cytoplasmic eIF5A has been proposed to promote proliferation in vulvar neoplasia, to facilitate the translation of proteins involved in autophagosome formation in breast cancer cell lines, or to be involved in leiomyomas pathogenesis." (PMID 38229033, 2024). "This increased spermidine level enhances hypusination of eukaryotic initiation factor 5 A isoform 1 (eIF5A) translation factor activating transcription factor 4 (TCF4) and increasing breast cancer aggressiveness." (PMID 39941901, 2025).
colorectal cancer (12 papers, 2014 to 2025). A primary or metastatic malignant neoplasm that affects the colon or rectum. "In conclusion, this study highlights EIF5A as a critical gene influencing radiation sensitivity and the TiME in colorectal cancer." (PMID 39290702, 2024). "We show here that hypusinated EIF5A promotes growth of colorectal cancer (CRC) cells by directly regulating MYC biosynthesis at specific pausing motifs." (PMID 33303756, 2020). "EIF5A was significantly upregulated in radioresistant colorectal cancer (CRC) tissues." (PMID 39290702, 2024). "Recently, eIF5A has also been indicated in colorectal cancer by regulating Myc synthesis." (PMID 39413959, 2024). "Indeed, recent reports suggest that inhibition of EIF5A hypusination with GC-7 can inhibit colorectal cancer growth." (PMID 38965534, 2024). "eIF5A's isoform eIF5A2 is upregulated in various cancer types including hepatocellular carcinoma, ovarian carcinoma, and colorectal carcinoma (CRC)." (PMID 28083147, 2016). "Sonia 29 reported that hypusinated EIF5A directly regulate MYC biosynthesis and promotes growth of colorectal cancer cells." (PMID 34234848, 2021). "eIF5A has negative correlation with survival rate in colorectal cancer patients compared with high expression of eIF5A gene." (PMID 35874632, 2022). "Knockdown of eIF5A or treatment with DHPs inhibitor (GC7) could inhibit the hypusination of eIF5A, which restrained the growth of colorectal cancer cells through arresting the synthesis of MYC protein." (PMID 35874632, 2022). "In addition, eIF5A has been shown to induce EMT in hepatocellular carcinoma and colorectal carcinoma." (PMID 25380840, 2014).
pancreatic cancer (12 papers, 2015 to 2024). "Additionally, in pancreatic cancer cells, mutational activation of K-Ras induced the expression of the eukaryotic translation initiation factor 5A (eIF5A) and consequent stimulation of ROCK1 and ROCK2." (PMID 34356110, 2021). "Different mechanisms have been proposed as mediators of the effect of eIF5A in pancreatic cancer, including facilitating the translation of a specific subset of proteins such as RhoA and Ras." (PMID 38229033, 2024). "For example, eIF5A regulates pancreatic cancer metastasis by modulating expression of RhoA and ROCK53." (PMID 33547280, 2021). "Over expression of EIF5A were found in many malignancies, such as pancreatic cancer 11, cervical carcinoma 12, esophageals quamous cell carcinoma 13 and gastric cancer." (PMID 34234848, 2021). "It is revealed that through the sHH signal pathway, EIF5A regulated the proliferation of pancreatic cancer." (PMID 34234848, 2021). "By stabilizing interactions with key residues, NPD11033 not only inhibits the deacetylase activity of SIRT2 but also impairs the proliferation of pancreatic cancer cells, as evidenced by the increased acetylation of its physiological substrate, eukaryotic translation initiation factor 5A (eIF5A)." (PMID 39682281, 2024). "In summary, here we show that eIF5A SUMOylation has an important impact on translation inhibition and SGs formation during stress as well as on the proliferative and migratory capacity of pancreatic cancer cells." (PMID 38229033, 2024). "Given their ability to impair tumor cell proliferation by modulating the acetylation of critical substrates like eIF5A, SIRT2 inhibitors represent a novel avenue for pancreatic cancer therapy." (PMID 39682281, 2024). "In pancreatic cancer epithelial cells, eIF5A is the upstream regulatory gene of PEAK1, and eIF5A may play a role by regulating PEAK1 signal." (PMID 33200656, 2020). "In addition, knockdown of eIF5A significantly inhibited endogenous PEAK1 and YAP1 expression, leading to tumor initiation in pancreatic cancer." (PMID 33200656, 2020). "Additionally, we’ve reported that the translation factor eIF5A drives PEAK1 protein production and can be targeted with the FDA-approved anti-fungal agent Cyclopirox Olamine (CPX) to both decrease cellular PEAK1 levels and abrogate pancreatic cancer cell growth." (PMID 26267863, 2015).
viral infection (12 papers, 2010 to 2025). "The eukaryotic translation initiation factor 5A1 (eIF5A1) and 5A2 (eIF5A2) are important proteins in a variety of physiological and pathophysiological processes and their function has been linked to neurodevelopmental disorders, cancer, and viral infections." (PMID 36848144, 2023). "We observed a significant upregulation in the levels of hypusinated eIF5A after infection with VSV and IAV, indicating that virus infection induces activation of eIF5A." (PMID 35967877, 2022). "By combining our new results with earlier knowledge regarding to host and viral controls of KSHV infection, we propose the following model describing the comprehensive roles of polyamine pathway and eIF5A hypusination in regulating KSHV viral infection." (PMID 35486659, 2022). "Here, we demonstrate that both virus infection and double-stranded RNA viral mimic stimulation induce the hypusination of eIF5A." (PMID 35967877, 2022). "So far, this is the first demonstration that poly I:C or virus infection triggers eIF5A hypusination." (PMID 35967877, 2022). "From initial descriptions of polyamines in bacteriophage virions to the elucidation of the mechanism by which eIF5A hypusination enhances Ebola virus replication, the breadth of our knowledge of polyamine-virus infection continues to expand." (PMID 32325677, 2020). "Perturbations in viral protein expression suggest that the antiretroviral activity of both drugs stems from their ability to inhibit hydroxylation of cellular proteins essential for apoptosis and for viral infection, exemplified by eIF5A." (PMID 24086341, 2013). "We first evaluated the eIF5A status in response to virus infection." (PMID 35967877, 2022). "However, transfection of cells with poly I:C also induces eIF5A hypusination, indicating that the activation of eIF5A can be mediated by dsRNA produced during virus infection." (PMID 35967877, 2022). "As a matter of fact, the entire process might be initiated by upregulation of eIF5A due to viral infection." (PMID 33807863, 2021). "So far, whether eIF5A plays a global role in viral infection is unknown." (PMID 35967877, 2022). "eIF5A hypusination may be then a mechanism by which polyamines regulate virus infection." (PMID 35967877, 2022). "In the present study, we reported that polyamine metabolism and eIF5A hypusination are modulated by KSHV, which in return promotes KSHV viral infection." (PMID 35486659, 2022). "Additionally, DEGs related to the response to viral infections, such as DDIT4, CXCR4, EIF5A, TNFAIP3, BCL2, and IRF1, were also upregulated in NBs." (PMID 38440735, 2024). "Interferon had been reported to induce depletion of polyamines and a decrease in the hypusine synthesis required for the activation of eIF5A, suggesting that activation of eIF5A in response to virus infection was not mediated by interferon signaling." (PMID 35967877, 2022). "Although the expression of the eIF5A protein is normally low, the Den-2 virus likely induces eIF5A overexpression in C6/36 cells, which is advantageous for cells' adaptation to viral infection without deleterious effects." (PMID 20819232, 2010). "More work and fresh clinical samples are needed to determine the expression of ODC-1, EIF5A, Hyp-EIF5A specifically in Th17, Treg, and TregDys in PLWH to achieve a complete understanding of how ODC-1-polyamine-EIF5A hypusination and the auto-regulatory loop impacts Th cells during viral infections." (PMID 36693889, 2023).
viral infection (continued). "Although eIF5A has not been investigated in relation to COX4 translation, it has been documented to promote other unconventional modes of translation initiation during virus infection and for specific cytoplasmic mRNAs." (PMID 35163207, 2022).